MRE11 (MRE11 double strand break repair nuclease)
Diseases named in the same sentence as MRE11 in open-access papers (continued):
Sharing a sentence is not in itself a finding about the gene and the disease.
serous cystadenoma (1 paper, 2017). A serous neoplasm in which the cysts and papillae are lined by a single layer of cells without atypia, architectural complexity or invasion. "Our finding is consistent with results of a previous study that demonstrated a reduced detection of MRE11, RAD50, and NBS1 in cancer tissue by immunohistochemistry as compared to the control group of healthy ovaries and serous cystadenomas." (PMID 28073364, 2017).
synucleinopathy (1 paper, 2022). A neurodegenerative disease that is characterized by the abnormal accumulation of aggregates of alpha-synuclein protein in neurons, nerve fibers or glial cells. "Elucidation of the pathway leading to the reduction of Mre11 would reveal the mechanism by which DNA damage accumulates during synucleinopathy." (PMID 35136202, 2022).
Telangiectasia (1 paper, 2024). Telangiectasias refer to small dilated blood vessels located near the surface of the skin or mucous membranes, measuring between 0.5 and 1 millimeter in diameter.
cancer (164 papers, 2009 to 2025). A tumor composed of atypical neoplastic, often pleomorphic cells that invade other tissues. "HCT116 cells carry a splicing mutation in the MRE11 gene and express lower levels of MRE11 protein than other cancer cell lines." (PMID 38360996, 2024). "This study confirmed the well-known fact that mutations in Mre11 are associated with the reduction or loss of other proteins of the MRN complex, which makes the specific role of Mre11 in cancer predisposition even more elusive." (PMID 37754262, 2023). "Our previous study showed that elevated MRE11 expression in OSCC patients was associated with adverse cancer progression, such as increased tumor stage and lymph node metastasis." (PMID 35629265, 2022). "MRE11 overexpression, commonly observed among cancer patients, has been postulated as a mechanism responsible for increasing cancer risk." (PMID 35328651, 2022). "In our results, a drastic increase in the number of MRE11 foci early after irradiation was generally associated with high cancer proneness." (PMID 35163494, 2022). "Our model is supported by several recently reported cancer-associated MR DNA DSB separation-of-function mutants that maintain Mre11 nuclease function while losing the ability to signal the presence of the DNA DSB through ATM or vice versa." (PMID 35084331, 2022). "We further demonstrated that WRNi-induced stalled forks undergo MRE11-mediated nucleolytic degradation in BRCA2-mutated cancer cells." (PMID 34772932, 2021). "Here in this paper, we focus primarily on the PTMs of MRE11 and their roles in DNA response and repair, maintenance of genomic stability, as well as their association with diseases such as cancer." (PMID 34440334, 2021). "Mutations to MRE11 are also linked to a variety of cancer types broadly characterized by chromosomal instabilities." (PMID 33782469, 2021). "Another MRE11 splice variant was described in a screen of mismatch repair-deficient cancer cell lines." (PMID 32668560, 2020). "MRE11 mutations and aberrant expression are associated with carcinogenesis and cancer treatment outcomes." (PMID 32523988, 2020). "To understand its role in tumor suppression, we characterized mutations affecting members of the Mre11 complex that were uncovered through cancer genomic analyses." (PMID 32187176, 2020). "Although the Mre11–Rad50–Nbs1 complex is essential, several spontaneous mutations have been noted in various cancers." (PMID 31889185, 2020). "Rapidly accumulating cancer genomic data has revealed that Mre11 complex components are mutated in approximately five percent of solid tumors." (PMID 32187176, 2020). "In this study, we used cancer genomic data to investigate the molecular mechanism(s) that underlie Mre11 complex-dependent tumor suppression using S. cerevisiae for genetic analysis as well as biochemical analyses of recurrent mutant gene products." (PMID 32187176, 2020). "As a result of this finding, RAD50, NBS1, and MRE11 were added to the MSKCC IMPACT (Integrated Mutation Profiling of Actionable Cancer Targets) gene list." (PMID 32187176, 2020). "Transfection of MRE11 in MRN-defective cancer cells rescues its deficiency in S-phase arrest in response to topoisomerase I inhibitor." (PMID 31767017, 2019). "During our analysis, we also identified some likely pathogenic variants in recently established cancer predisposition genes, such as MRE11 and CTR9." (PMID 31214250, 2019). "It is suspected that MRE11 deficiency causes microsatellite instability through defective interactions with MLH1 and MRE11 leading to their inactivation in MMR-deficient cancers." (PMID 30769804, 2019). "A series of publications have shown that suppression of homologous recombination repair by HDACi treatment, including SAHA and homologous recombination associated RAD50 and MRE11 suppression, were observed in cancer cells only." (PMID 29414878, 2018).
cancer (continued). "Since the formation of mitotic chromatin bridges and lagging chromosomes in HR-deficient cancer cells are a likely consequence of disturbed replication fork integrity, we tested the involvement of Mre11 and PTIP." (PMID 28714471, 2017). "Another member of the MRN complex, MRE11, was implicated in cancer predisposition in a number of patients." (PMID 26455503, 2016). "Specifically, germ-line mutations in either NBS1 or MRE11 give rise to the cancer-predisposing inherited disorders Nijmegen breakage syndrome and ataxia-telangiectasia-like disorder (ALTD), respectively." (PMID 27335639, 2016). "A small subset of HR deficient cancers have been found to have MRE11 mutations providing a rare confounder while supporting the potential of low MRE11 as a biomarker of HR behavior." (PMID 26198537, 2015). "They showed low MRE11 protein expression was associated with worse cancer-specific survival following radiotherapy." (PMID 26198537, 2015). "Loss of MRE11 expression has been suggested to sensitize colorectal, breast and haematological cancer cell lines to PARP-inhibitors due to impaired HR DNA repair." (PMID 24927325, 2014). "Previous reports have indicated genetic MRE11 abnormalities to be linked to development of various cancers, but protein levels have rarely been studied in SOC." (PMID 24752797, 2014). "BRCA1/2 somatic mutation or promoter methylation, ATM mutation, MRE11-dominant negative mutations in MMR-deficient cancers, FANCF promotor methylation and PTEN deficiency are all potential biomarkers of sensitivity to PARPi." (PMID 24616882, 2014). "In the selected fragments of the RAD50 and MRE11 genes, which have been reported to harbor mutations in cancer, we were unable to confirm the occurrence of the formerly known mutations in our group of either ALL or AML cases." (PMID 24093751, 2013). "We selected 20 yeast orthologs of CIN genes that are recurrently mutated in various cancers (e.g., CDC4, MRE11, cohesins) or are represented in the cancer gene census." (PMID 23390603, 2013). "In conclusion, current results demonstrate that RAD50/MRE11 variants occur at very low frequency in analyzed group of cancer patients in Poland." (PMID 24079363, 2013). "Similarly, in BACA2-deficient breast cancer cells, WRN helicase protects against the over-degradation of stalled forks in BRCA2-deficient cancer cells by inhibiting the activity of MRE11 and EXO1 nuclease on the degenerating forks." (PMID 39759116, 2025). "Germline mutations in MRE11, although rare, can predispose an individual to cancer." (PMID 37446144, 2023). "It is noteworthy that high numbers of MRE11 foci assessed early (first hour) post-irradiation have been observed in cells from syndromes associated with cancer proneness while high numbers of MRE11 foci assessed 24 h post-irradiation is a common feature of cells from degenerative diseases." (PMID 38136617, 2023). "Our previous results showed that single-nucleotide polymorphisms (SNPs) in the 3′ untranslated region (3′UTR) microRNA (miRNA) binding sites of MRE11 gene are associated with decreased cancer risk but with shorter survival of CRC patients, which implies the role of miRNA regulation in CRC." (PMID 36324569, 2022). "Meanwhile, we used reconstituted reactions to test whether these cancer-related mutations affect MRE11 nuclease activity, and found K255E/K384Q protein exhibited a minor nuclease activity impairment compared with WT MRE11." (PMID 36050397, 2022). "Firstly, somatic mutations of MRE11 have been identified in different types of cancer." (PMID 34440334, 2021). "Although elevated MRE11 expression was associated with a more malignant cancer phenotype, disparate MRE11 nuclease and non-nuclease activities were found to mediate distinct aspects of the cancer phenotype." (PMID 33927349, 2021).
cancer (continued). "We reasoned that additional functional analyses of Mre11 complex mutations arising in human cancer could provide insight regarding the mechanism(s) of Mre11 complex function including its role in tumor suppression." (PMID 32187176, 2020). "Indeed, in BRCA2-deficient cancer cells, unprotected regressed arms become the entry point for MRE11, whose recruitment is performed by RAD52, which binds MRE11." (PMID 32050645, 2020). "Additionally, sporadic mutations in MRE11 have been observed in different cancers, including colorectal, breast, and ovarian, that contain chromosomal instabilities (e.g., translocations and end-joining)." (PMID 32668560, 2020). "Components of the Mre11 complex are mutated in approximately five percent of human cancers." (PMID 32187176, 2020). "However, heterozygous carriers of mutations in Mre11, Rad50, Nbs1/Nbn have only a small increase in cancer incidence over the lifecourse." (PMID 32954257, 2019). "As a core protein of the MRN repair complex, MRE11 may also be associated with the prognosis and development of human cancers." (PMID 31221177, 2019). "Interestingly, MRE11 overexpression, commonly observed among cancer patients, has been postulated as a mechanism responsible for increasing cancer risk." (PMID 26735576, 2016). "Polymorphic variation in Mre11 may also be associated with increased cancer predisposition." (PMID 35853939, 2022). "In addition, PARP1/2 themselves are critical for Mre11-dependent replication restart at stalled replication forks, and their inhibition by PARPi also causes genome instability and synthetic lethality in HR-deficient cancer cells." (PMID 35270034, 2022). "In addition, BRCA1/2-deficient cancer cells may develop PARPi resistance by protecting their replication forks; they achieve this by blocking the recruitment of nucleases, MRE11 or MUS81, to the stalled fork, thereby resulting in fork protection." (PMID 36499000, 2022). "In addition, the dysregulation of MRE11 is strongly associated with cancer." (PMID 34440334, 2021). "High MRE11 expression levels on immunohistochemistry have been associated with improved cancer-specific survival in radiotherapy patients compared to high MRE11 expression in patients undergoing cystectomy alone, also suggesting a role for epigenetic alterations in MRE11 in radiotherapy response." (PMID 28055970, 2017). "This peptide presents evident inhibition of MRE11 K673la and impairs HR, which in turn promotes cancer cell sensitivity to chemotherapy." (PMID 40563450, 2025). "MRE11 and RAD50, which are involved in dsDNA repair, are mutated by frameshift mechanisms in their microsatellite loci in MSI cancer subsets." (PMID 40573300, 2025). "High MRE11 lactation can promote HR and chemical resistance of cancer cells, whereas inhibition of MRE11 lactation can weaken HR and promote the sensitivity of cancer cells to chemotherapy." (PMID 39991762, 2025). "In line with this, in vitro data showed that cancer cells expressing MRE11 K673R mutant exhibited inefficient DNA damage repair and increased genomic instability compared to those expressing MRE11 WT." (PMID 39872378, 2024). "In this regard, we recently discovered an actionable vulnerability in ZEB1high cancer cell sub-populations by inhibiting the DDR nuclease MRE11." (PMID 38937629, 2024). "Due to the potentially high toxicity of targeting CBP or LDH, the authors sought to develop an alternative strategy specifically targeting MRE11 K673 lactylation for cancer therapy." (PMID 39872378, 2024).
cancer (continued). "A paralog of SERPINE1, SERPINE2, has been recently reported to participate in DNA repair process through the direct interaction with ATM and MRE11 to protect cancer cells from IR-induced DNA damage." (PMID 36681663, 2023). "When PARPi acts on BRCA-mutated cancer cells, it causes synthetic lethality through inhibition of the DDR pathway, while simultaneously inhibiting meiotic recombination 11 (MRE11), which degrades RF by blocking its interaction." (PMID 37950047, 2023). "Given its essential role in DNA repair, it is possible that MRE11 helps cancer cells withstand and survive DNA-damaging assaults from chemoradiotherapy." (PMID 37173905, 2023). "Here, we investigated the prognostic value of MRE11, an essential DDR protein that has been implicated in the development and evolution of numerous cancers, including CRC." (PMID 37173905, 2023). "As CD44 is a hallmark for cancer stemness in a number of cancers, including OSCC, we further examined the ability of cancer stem cell-like growth in OSCC cells under the influence of differential MRE11 expression levels." (PMID 35629265, 2022). "Together, these data indicate that SUMOylation of MRE11 ensures DNA end resection and HR efficiency, which is closely related to genome stability and cancer development." (PMID 36050397, 2022). "Aberrant degradation of nascent DNA by MRE11 was observed in tumor suppressor BRCA1/2-deficient cells, and abrogation of MRE11 activity is linked to PARP inhibitor resistance in cancer chemotherapy." (PMID 35501303, 2022). "The abrogation of MRE11 activity in BRCA1/2-deficient cells, on the other hand, was linked to PARP inhibitor resistance in cancer chemotherapy." (PMID 35501303, 2022). "The ability of tumorsphere formation, which represents cancer cell growth from self-proliferation, was enhanced in MRE11-overexpressing CAL-27 and Ca9-22 cells, respectively." (PMID 35629265, 2022). "The clinical importance of HR for cancer therapy, mainly of MRE11, RAD50, and, NBS, has already been reported." (PMID 36324569, 2022). "The current study further investigated the potential involvement of cancer stemness in these MRE11-promoting effects, leading to the findings of CD44 as a downstream effector of MRE11." (PMID 35629265, 2022). "We further show that cancer-related MRE11 mutants with impaired SUMOylation exhibit compromised DNA repair ability." (PMID 36050397, 2022). "Further structural modification of Mirin resulted in PFM01 and PFM03 as selective endonuclease inhibitors and PFM39 which selectively block the exonuclease activity of MRE11, while their potential function in cancer therapy remains poorly explored." (PMID 35463312, 2022). "It has also been found that MRE11 downregulation impairs the repair capacity of radiation-induced DSB in cancer cells." (PMID 33195247, 2020). "The goal of this study was to query this database and map all MRE11, RAD50 and NBS1/NBN mutations appearing in cancer cells." (PMID 33339169, 2020). "Here we identify mutation hotspots in MRE11, RAD50, NBS1/NBN, and CtIP from analyzed cancer data on COSMIC." (PMID 33339169, 2020). "Intriguingly, mRNA expression of ATM and Mre11 was upregulated in tumor tissue compared with matched samples in some cancer types but downregulated in other cancer types." (PMID 32111912, 2020). "Other proteins with verified roles in DNA metabolism and cancer development that contain RGG motifs include Mre11 (a DSB-processing enzyme), Mll4 (a histone methyltransferase), and Ews (Ewings sarcoma protein; DNA damage response protein)." (PMID 33106247, 2020). "The data presented here highlights differences in the evolution of MRE11, RAD50 and NBS1/NBN and identify key mutation hotspots within cancer samples." (PMID 33339169, 2020). "Previous studies have found that AKT promotes DNA repair in cancer cells by upregulating MRE11 expression following exposure to ionizing radiation." (PMID 33195247, 2020).